CD44 (CD44 molecule (IN blood group))
Diseases named in the same sentence as CD44 in open-access papers (continued):
Sharing a sentence is not in itself a finding about the gene and the disease.
cancer (continued). "In PCA, not only elevated β-catenin expression is found in the cancer cell nucleus, but Wnt signal promotes cell self-renewal in several cell models including LNCaP, C42B, and PC3 cells in an AR-independent way, increasing expression of CD133 and CD44." (PMID 37175453, 2023). "Furthermore, we noticed that the protein levels of cancer stem cell markers ALDH1 and CD44 were also decreased in the M1-20-treated cancer tissues, implicating that the population of cancer stem cells in the grafted cancers were altered by the M1-20 treatment." (PMID 37598210, 2023). "In addition, AEC-CCo-CP-Fe-bLf NCs in the diet reduced the cancer markers of malignity of the Caco-2 cell (CD3133, EpCAM, and CD44)." (PMID 37259362, 2023). "In order to further confirm whether TM4SF1 is related to the cancer stem of HCC, we isolated CD133+, CD44+ and CD133+/CD44+ cells from LM3 cells with silenced TM4SF1 and LM3 cells from untreated group by flow cytometry." (PMID 37069693, 2023). "This research established a relationship between CD44 and TMB and MSI, implying that CD44 may provide a more comprehensive perspective of immunotherapy in these cancer types." (PMID 37117249, 2023). "Previous research showed that the glycosylation of CD44, rather than its overall expression, controls the adhesion of cancer cells to HA, as well as the extent and affinity of this binding." (PMID 37958796, 2023). "This could enable the measurement of expressions of certain molecular markers, such as the epithelial marker cytokeratin 19, mesenchymal marker plastin 3, and cancer stem markers ALDH1, CD133, and CD44." (PMID 36835361, 2023). "It appears that only a proportion of CD44, not all, are modified by ofCS in cancer patients, which can be specifically detected by rVAR2." (PMID 36746966, 2023). "Among these CD44 positive cells, no cell exhibited phenotype similar to cancer stem cells (CSCs) with CD44highCD24low markers, whereas 99.9% cells displayed CD44highCD24high phenotype or a non-CSCs like phenotype." (PMID 38062442, 2023). "Importantly, the positive populations for CSCs markers such as CD133, CD44, and CD24 were determined in the whole population of cancer cells." (PMID 37958844, 2023). "Thus, CD44 and ICAM1 both have been studied extensively as selective therapeutic targets in the field of cancer therapy and prevention." (PMID 37190316, 2023). "There are many AS events involves in EMT during cancer progression, such as splicing of FGFR2, CD44, CTNND1, and ENAH and they may become therapeutic points- it is therefore timely to ask ourselves: Can these AS events in EMT be targets of cancer therapy?" (PMID 38002944, 2023). "Following a known, comprehensible signaling chain, the expression of phosphorylated NF-kB (p-NF-kB) as main inflammation parameter, vascularisation factor VEGF as well as CD44, CD133 and ALDH1 as cancer stem cell marker were comparable within each CRC cell line." (PMID 36902421, 2023). "Unlike many cancers, in which mesenchymal character correlates with stem-like phenotype, we and others have observed that CD44+ epithelial cells serve as cancer stem cells in EOC." (PMID 37568736, 2023). "Moreover, HA can form a triple complex with CD44 and TLR2 to promote the invasiveness and pro-inflammatory environment in cancer cells." (PMID 37234812, 2023). "CD44 and CD24 are also used to characterize cancer stem cells." (PMID 37529165, 2023). "In particular, the shift of CD44 isoforms is required for epithelial to mesenchymal transition (EMT) and is crucial for the maintenance of pluripotency in normal human cells and the acquisition of cancer stem cells phenotype for malignant cells." (PMID 38106992, 2023). "Future clinical trials are warranted to compare the response to statins between cancer patients with or without CD44+ CTC clusters." (PMID 37866630, 2023).
cancer (continued). "In cancer therapy, CSCs have been intensely researched in recent years, and CSC markers, such as CD44 and CD133, have been shown to be enhanced in three-dimensional spheroid cultures than in two-dimensional monolayer cultures, since these cultures mimic the in vivo microenvironment." (PMID 37012331, 2023). "CD44 is a non-kinase family and single-transmembrane glycoprotein that has been widely accepted as a requirement for cancer stem cell maintenance." (PMID 37000153, 2023). "Such therapy effectively suppressed CD44 mRNA and protein levels, thus reducing the population of CD44-positive cancer stem-like cells, and it had no serious side effects." (PMID 38201468, 2023). "In the Phase II, CD44 and SNA-1 showed highest AUC (>0.85) in differentiating cancer/HGD from LRLs." (PMID 37747904, 2023). "To further validate whether CBX2 and CEP55 affect malignant cell stemness, we reanalyzed the public datasets related to HCC CSC and observed that CBX2 and CEP55 levels were higher in cancer stem cells that were CD133, ALDH, or CD44-labeled." (PMID 37980163, 2023). "In addition to the classic biomarkers, such as CD133, CD44, epithelial cell adhesion molecule (EpCAM), and CD90, other biomarkers have also been studied in specific cancers." (PMID 38164743, 2023). "The CD44-targeted nanoparticles containing CME may enhance the anticancer effect of the extract and selectively target CD44 receptor-overexpressed cancer cells." (PMID 37376218, 2023). "In fact, high CD44 expression with high binding and uptake activities is not limited to cancer cells." (PMID 38140012, 2023). "Moreover, claudin-low cancers display low expression of epithelial surface molecules CD24 and EpCAM and high expression of CD44 and CD49f." (PMID 37345027, 2023). "Due to their inherent fluorescence properties QDs can be used in real-time fluorescent imaging of cancer cells by detecting specific cancer markers, such as HER2, PSA, folic acid, and CD44, etc., by attachment of peptide, monoclonal antibody or receptor-specific ligand to the QDs." (PMID 38112935, 2023). "CD44 and CD24 are engaged in different functions during cancer metastasis and progression." (PMID 37664387, 2023). "However, an upregulation of cancer stemness markers such as SOX9, CD44, and CD9 implies that GBM is potentially moving towards cancer-specific stemness in the presence of NSCs." (PMID 36834653, 2023). "Scientists were able to identify a minor fraction (0.2–0.8%) of carcinoma cells, co-expressing CD24, CD44 and epithelial-specific antigen (ESA) and featuring high tumorigenicity, self-renewal capabilities and the ability to produce phenotypically diverse cancer cells." (PMID 37108193, 2023). "CD44, being specifically localised in cancer cells rather than borderline serous tumours, emerges as a suitable therapeutic target marker with a focus on cancer stem cells (CSCs) in high-grade serous ovarian carcinoma (HGSC)." (PMID 38201468, 2023). "Many therapeutic efforts with Ab–NPs focus on cancer and on improving survival in vivo, by targeting EGFR, CD44, mucin 1 C terminus, HER2 (which are overexpressed in a variety of cancers such as breast and lung cancers), and death receptor 5 (which are overexpressed in pancreatic cancer)." (PMID 37849659, 2023). "In addition, physiological levels of BMP9 (2‐5 ng/mL) promote EpCAM+ cancer stem cell (CSC) properties in Huh7 cells, but high levels (200 ng/mL) inhibit CD44+ CSC properties in Hep3B cells." (PMID 37132170, 2023). "There is growing evidence that RT-induced K-RAS/ERK signaling activation elevates CD44 expression through downregulation of miR-202 and miR-185 expression, promoting SRC activation to drive cancer stemness and EMT as a pivotal mechanism to mesenchymal transition in GBM cells." (PMID 37637066, 2023).
cancer (continued). "In mechanism, elevated expression of TCF3 in cancer cells led to the upregulation of Inhibitor of DNA binding 1 (ID1) and finally promoted ESCC cell growth by inducing cancer stemness and enhancing the expression of CD44 and CD133." (PMID 37607071, 2023). "CD44, as a prognostic marker, is of great significance for clinical diagnosis and cancer treatment, and Neuropilin-1(NRP1) is a checkpoint target with unique implications for cancer immunology and immunotherapy." (PMID 37251370, 2023). "We found that CD44, an established cancer stem cell marker known to promote EMT54,55, was most highly expressed in the hEMT state across TCGA cancers, and elevated levels of several other stemness signatures most often accompanied the hEMT and MES macro-states." (PMID 36774358, 2023). "In a cancer progression model using NIH3T3 fibroblastic cells containing Ras family mutants (H-RasV12 and Rit79L), for instance, OPN is overexpressed, promoting overexpression of CD44." (PMID 36769264, 2023). "In vitro studies have demonstrated that these nanogels exhibit significant antitumor activity against cancer cells, without negative effects on normal cells with low CD44 expression." (PMID 38140012, 2023). "Moreover, AC133 monoclonal antibody (mAb) and anti-CD44 antibody conjugated with IRdye700 agents were used for NIR-PIT against different cancers by targeting cancer stem cell marker AC133 and CD44, respectively." (PMID 36768976, 2023). "Notably, treatment with M1-20 leads to down-regulation of cancer stem cell markers including ALDH1 and CD44, suggesting its potential in modulating cancer stem cell populations." (PMID 37598210, 2023). "Generally, CSCs exhibit the expression of CD133, CD44, EpCAM, and ALDH in most cancers." (PMID 37853437, 2023). "CD44 is expressed on the surface of many cell types, including immune cells such as T cells and B cells, and is the most common cancer stem cell (CSC) marker in multiple types of cancers." (PMID 36982699, 2023). "Furthermore, GSK J4 treatment significantly reduces the occupancy of KDM6B on promoters of both SOX2 and CD44, suggesting the KDM6B-driven regulation of these stemness genes in detached cancer cells." (PMID 35186918, 2022). "In the hypercholesterolemic urinary bladder cancer (UBC) mouse model, ezetimibe significantly suppress HFHC-induced serum lipid (TC, LDL-C, and ox-LDL), and decrease the percentage of cancer cells (CK5+, CK14+, and p-STAT3+) and cancer stemness markers (ALDH1A1, CD44, KLF4, and Nanog)." (PMID 35924044, 2022). "Therefore, we looked at the expression levels of cancer stem-like marker gene and YAP target CD44 using data from an mRNA sequencing we previously performed with three of our HNSCC cell lines." (PMID 35054968, 2022). "Furthermore, regarding the CD44-targeted cellular uptake ability, smaller NPs were shown to be internalized more rapidly in MCF-7 cancer cells than medium to larger NPs." (PMID 36091467, 2022). "We further demonstrated that targeting short O-glycoforms such as the Tn and sialyl-Tn antigens was key to overcome the lack of cancer specificity presented by CD44." (PMID 35547758, 2022). "However, the data on the expression of stem cell markers CD44, CD24, and ALDH1A1 in benign breast tissue of cancer-free women remains extremely limited." (PMID 36590957, 2022). "Fibrocytes that were identified in lung tumors as CD45+CD44+CD162+CD11b+F4/80+CCR2/5+CD9+ cells had lost the monocyte marker Ly6C compared to bone marrow fibrocytes, indicating a maturation process in the cancer microenvironment, reminiscent of monocyte to macrophage differentiation in tumors." (PMID 36241617, 2022). "Cancer stem cells are a small-specific subpopulation characterized by self-renewal and differentiation capabilities and are identified by the expression of distinct cell surface markers such as CD133, CD44, CD90, CD24, and CD73." (PMID 35713728, 2022).
cancer (continued). "As for cell–matrix interactions, CD44 appears as a possible candidate since it is expressed by neoplastic pTECs preferentially in 3D cultures as well as in aggressive TETs in vivo and—together with WNT4—is a marker of cancer stem cells." (PMID 35965500, 2022). "Consistent with our in vitro studies, IHC staining of mice liver tissue showed that TSG-6 could increase CD44 and α-SMA expression in cancer cells and fibroblasts, respectively." (PMID 35280699, 2022). "In addition, CD44, as a marker of CSCs and a vital regulatory factor in the EMT program, has a key role in mediating cancer metastasis and therapeutic resistance through activating and modulating several cell signaling networks." (PMID 36678534, 2022). "Cluster of differentiation 44 (CD44) is an adhesion molecule in cancer stem cells that does not seem to be involved in stem cell properties and interacts with xCT." (PMID 36457557, 2022). "Moreover, HA can interact with various cell-surface receptors, notably CD44 and RHAMM, which are well established to be involved in cancer cell survival, motility, and metastasis." (PMID 36612261, 2022). "The aim of our study was to investigate the correlations between the proliferation index determined by Ki-67, expression of CD44, MMP2, and MMP9 and analyze the interactions between the cancer stem cells and metalloproteinases as potential prognostic markers in pRCC and chRCC." (PMID 36079127, 2022). "These NGs demonstrated higher cytotoxicity in CD44-expressed MDR human breast and pancreatic adenocarcinoma cells by internalization of NGs via CD44 receptor-mediated endocytosis, and by the interaction with the cancer cell membrane." (PMID 36559325, 2022). "In agreement with this, we demonstrated that NEAT1v1 increased CSC makers, such as CD13, CD44 and CD90, in irradiated cells, suggesting that NEAT1v1 might induce cancer stemness to protect HCC cells from radiation." (PMID 35054896, 2022). "The transmembrane protein CD44 is widely recognized as a BCSC marker in breast and other cancers." (PMID 35504883, 2022). "Interaction between HA and its receptors, CD44 and HMMR, participates throughout the course of cancer progression and metastasis including cancer cell proliferation, adhesion, migration, differentiation and stem cell maintenance, thus playing an important role in tumor development and metastasis." (PMID 36002694, 2022). "From the newly generated lists of RBP-specific AS targets, we selected CD44 and NUMB for further analysis, based both on their ESRP1-specific AS patterns and on their well-established roles in EMT, stemness/differentiation, and cancer progression." (PMID 36346211, 2022). "Moreover, targeting cancer stem cells (CSC), or cancer-initiating cells, was believed to be a curable way to eradicate cancers, and CD44 was one of the CSC markers for some cancers." (PMID 35436988, 2022). "miR-141 targeted CD44, members of Rho GTPase signaling pathway (RAC1, CDC42, CDC42EP3 and ARPC5) and EZH2 mRNAs implying possible mechanisms of its influence on invasion, cell motility, and on cancer stem cells properties." (PMID 36429127, 2022). "The invasion of cancer cells to the perivascular environment relies on their motility, in which motility-involving molecules such as ARP2/3, L1CAM, serpins, CD44, CDC42, CXCR4, epidermal growth factor receptor (EGFR), as well as Wnt7 signaling, are critical players." (PMID 36119528, 2022). "Moreover, the concurrent overactivation of CD147 and CD44 strongly sparks AKT pro-survival signaling, protecting circulating cancer cells from anoikis and strengthening their resistance to chemotherapy and/or radiotherapy." (PMID 35955471, 2022).
cancer (continued). "Increased CD44 and PTGER4 in many cell types such as macrophages, DCs, cancer cells, and T cells were correlated to upregulated SPP1 in macrophages; the activated interaction pairs were correlated to cancer immune escape and metastasis." (PMID 35874770, 2022). "Recent studies have revealed that both hyaluronan and CD44/CD44v6 stimulate drug resistance by promoting transcriptional up-regulation of the MDR1 gene and the stimulation of multidrug resistance expression in different cancer types." (PMID 36330477, 2022). "Moreover, LPA treatment in the cancer cells stimulated the CSC-related gene signature, via the PKD signaling, including CD133 and CD44, two common CSC markers, whose expressions are connected with a poor prediction in pNET patients." (PMID 36497140, 2022). "Another interesting approach could be to suppress CD44 and CDC42, which might impair VCO by impeding the cancer cell-pericyte fusion." (PMID 36119528, 2022). "CSCs, in concert with C10, were involved in non-canonical WNT signaling cascades in CD44+ cancer cells, endothelial cells and fibroblasts." (PMID 36451812, 2022). "CD44 is a cell surface adhesion receptor (not an integrin) and is largely recognized as a cancer stem cell (CSC) marker expressed by almost every tumour cell." (PMID 35800896, 2022). "Bioinformatics analysis revealed that these effects of Id2 on cancer progression might be regulated by focal adhesion kinase (FAK) signaling and CD44/Twist expression." (PMID 35982951, 2022). "In addition, CD-44 and c-Myc were downregulated in TGF-B/atropine-treated cells relative to the TGF-B treated ones in both cancer cell lines." (PMID 36077256, 2022). "As CD44 is overexpressed (OE) in BCSCs and responsible for various aspects of cancer progression, such as CSC stemness, tumor recurrence, and metastasis, it is also considered a promising target for cancer treatment." (PMID 35504883, 2022). "Several of the most often used cancer stem cell markers in the recruited studies, including ICAM-1, CD133, CD90, CD44, CK19, and Nanog, were evaluated to determine whether CCSCs may possibly be employed for HCC prognostic prediction." (PMID 35884432, 2022). "Similarly, the decreased levels of SOX4, SOX9, Nanog,CD44, KLF4 and ABCG2 were observed from the harvested KYSE450 tumors related to miR-637 overexpression, indicating the inhibition of cancer cell stemness by miR-637." (PMID 36329557, 2022). "CD44 is upregulated during EMT and in stem cells, and promotes cancer progression and metastasis." (PMID 36418889, 2022). "To investigate whether compound 1 contributes to the reduction of the cancer stem cells (CSC) number, we determined CD44+/CD24− subpopulation in both the cell lines." (PMID 36232754, 2022). "Moreover, CD44 and Stat3 acted as the top DEPs, and the expression and activity of which are correlated with EMT in different cancers." (PMID 36678534, 2022). "Furthermore, PGCCs can give rise to regular-sized cancer-cell progeny through asymmetric budding, which show expression of CSC markers CD44 and CD133." (PMID 35563313, 2022). "In addition, NF-κB downstream effectors, such as CCND1, CCNE2, MET, VEGFA, CD44 and CD133, contribute to cancer proliferation, metastasis and stemness, and their expression is regulated by PCDH1." (PMID 35864095, 2022). "From our big data studies validated with independent datasets, protein-coding hub genes FN1, CD44, TIMP1, SNAI2, and SPARC were found significantly enriched in signal transduction, proteolysis, cell adhesion and proteoglycans pathways in cancer as well as the PI3K/Akt-signaling pathway." (PMID 35534592, 2022). "Hence, the role of CD44 in cancer drug resistance in CD44 knockdown MDA-MB-231 and ZR75 cells, along with CD44-overexpressed MCF7 and ZR75 cells, was evaluated by using chemotherapy drugs, including fluorouracil (5-FU), paclitaxel, and doxorubicin." (PMID 36289750, 2022).